KRT5 (keratin 5)
Diseases named in the same sentence as KRT5 in open-access papers (continued):
Sharing a sentence is not in itself a finding about the gene and the disease.
colon cancer (3 papers, 2020 to 2023). "In future, we will conduct additional clinical studies and in vivo experiments to further explore the role of TRIM29/KRT5 axis in colon cancer progression." (PMID 37671092, 2023). "However, the association between TRIM29 and KRT5 in colon cancer remains unclear." (PMID 37671092, 2023). "After KRT5 overexpression, the cell viability and colony formation of colon cancer cells significantly decreased." (PMID 37671092, 2023). "Using immunohistochemistry and PCR, we found that KRT5 expression was significantly decreased in colon cancer tissues." (PMID 37671092, 2023). "KRT5 silencing neutralises the inhibitory effects of sh-TRIM29 on colon cancer cell growth." (PMID 37671092, 2023). "Similarly, compared to that in NCM460 cells, KRT5 was significantly downregulated in colon cancer cells, especially in SW480 and HCT-116 cells." (PMID 37671092, 2023). "Thus, targeting TRIM29-mediated ubiquitination levels of KRT5 might be a new direction for colon cancer therapy." (PMID 37671092, 2023). "In the YUMC-C1 and YUMC-C2 drug-resistant and metastatic colon cancer cells, respectively, metastatic genes (CDH2, KRAS, CDC42, MCPH1, SRGAP) and markers of stemness (BRACA1 and 2, CD44, KRT5, WNT4, CD29, SAL4) were markedly enhanced." (PMID 33050525, 2020). "KRT5 knockdown neutralises the inhibitory effect of sh-TRIM29 on colon cancer cell growth and TRIM29 knockdown prevented the proliferation of colon cancer cells by decreasing ubiquitination of KRT5, which enhanced the protein stability and expression of KRT5 in cancer cells." (PMID 37671092, 2023).
Dowling-Degos disease (3 papers, 2020 to 2024). A pigmentation disease characterized by a reticulate pattern of abnormally dark skin coloring, particularly in the body's folds and creases. "A significant aspect of this review is the exploration of the genetic, histopathological, and clinical parallels between GGD and Dowling-Degos disease (DDD), which is another rare autosomal dominant genodermatosis, particularly focusing on their shared mutations in the KRT5 and POGLUT1 genes." (PMID 38390850, 2024). "However, patients with type-1 Dowling-Degos disease (DDD1; OMIM#179850), a genodermatosis caused by mutations in the keratin 5 (KRT5) gene, possess keratinocytes that incorporate melanin pigments but lack nuclear caps, suggesting a role for KRT5 in melanin positioning." (PMID 38589876, 2024).
Fibroadenoma (3 papers, 2012 to 2025). A benign tumor of the breast characterized by the presence of stromal and epithelial elements. "KRT5, TGF-β, PAI-1, HIF-1α, TIMP1, MMP2, TWIST1, VEGFα, and BRCA2 were all significantly upregulated in fibroadenomas." (PMID 40806434, 2025).
keloid (3 papers, 2017 to 2025). An irregularly shaped, elevated mark on the skin caused by deposits of excessive amounts of collagen during wound healing. "We performed immunohistochemical staining using anti-Filaggrin, anti-Protein Gene Product 9.5 (anti-PGP9.5), and anti-Cytokeratin 5 antibodies to analyse the nerve fibres extension into the epidermis in the peripheral regions of the anterior chest keloids." (PMID 40830367, 2025). "Most keratins were downregulated in keloids, including KRT10, KRT14, KRT15, KRT19, KRT1, KRT77, and KRT5." (PMID 35435317, 2022).
Obesity (3 papers, 2021 to 2025). Accumulation of substantial excess body fat. "TP73, PIK3R2, SLC9A3R1, KRT5, KRT14 and TFAP2C are novel biomarkers for pathogenesis of obesity associated type 2 diabetes mellitus." (PMID 33902539, 2021). "Moreover, the levels of Krt5 and several keratin and desmosome genes are suppressed in obesity and in type 1 diabetes in the mouse, leading to obesity-associated skin fragility." (PMID 34572017, 2021).
Palmoplantar keratoderma (3 papers, 2022 to 2025). Abnormal thickening of the skin of the palms of the hands and the soles of the feet. "Severe EBS results from mutations in KRT5 and KRT14 and is characterised by skin fragility, herpetiform blistering, and the development of confluent palmoplantar keratoderma and nail dystrophy." (PMID 40700032, 2025).
urothelial bladder cancer (3 papers, 2021 to 2024). "NanoString-based gene expression analysis using typically luminal (GATA3+/KRT20+) and basal markers (KRT14+/KRT5+/GATA3low/-/KRT20low/-) classified urothelial bladder carcinoma samples as luminal, basal, and a third category (KRT14-/KRT5-/GATA3-/KRT20-), null/double negative (non-luminal/non-basal)." (PMID 34771663, 2021).
amyloid (2 papers, 2021 to 2022). "The exclusively cutaneous forms of amyloidosis caused by cytokeratin 5 – CK5 deposition (macular amyloidosis and lichen amyloidosus) do not progress to systemic disease." (PMID 34544639, 2021).
basal cell carcinoma of the skin (2 papers, 2016 to 2022). "Krt5-Gli2 transgenic mice develop multiple basal cell carcinomas of the skin that are characterized by robust expression of KRT17 in the tumor cells." (PMID 27512993, 2016).
bladders (2 papers, 2008 to 2017). "Moreover, the overexpression of cyclooxygenase-2 driven by keratin 5 promoter causes spontaneous inflammation and is related to hyperplasia and carcinomas in urinary bladders." (PMID 28415579, 2017).
bronchiectasis (2 papers, 2018 to 2024). Segmental, irreversible dilation of the bronchial tree resulting in the accumulation of secretions which leads to obstruction. "In this study, we collected pulmonary tissues from 5 patients with bronchiectasis through surgical excision and performed immunostaining to examine the P63+ KRT5+ cell distribution in the lung." (PMID 39566467, 2024). "Regarding bronchiectasis, previous studies have indicated the expansion of P63+ KRT5+ lung basal progenitor cells in dilated bronchioles." (PMID 39566467, 2024). "Altogether, these observations suggested that the P63+ KRT5+ progenitor cells might have alveolar repair function in the lungs of some patients with bronchiectasis, probably in those patients with recent disease onset and no active infection in the lung." (PMID 39566467, 2024).
Cachexia (2 papers, 2016 to 2022). Severe weight loss, wasting of muscle, loss of appetite, and general debility related to a chronic disease. "Our previous work, showing that β3-adrenoreceptor antagonism decreases WAT browning and ameliorates cachexia in the genetic keratin 5-son of sevenless (K5-SOS) model of CAC, argued for the involvement of β-adrenergic signaling in adipocytes during WAT browning causing the pathogenesis of CAC." (PMID 35210363, 2022).
colorectal cancer (2 papers, 2022 to 2024). A primary or metastatic malignant neoplasm that affects the colon or rectum. "KRT5, or cytokeratin 5, is typically expressed in basal cells such as myoepithelial and basal keratinocytes, and is uncommon in colorectal cancer." (PMID 39011470, 2024).
diabetes (2 papers, 2021). "Therefore, promoting the differentiation of more pancreatic Krt5+ cells into functional beta cells through the regulation of Notch activity might be a novel strategy to reduce the incidence of prediabetes/diabetes after AP." (PMID 34556631, 2021).
esophageal adenocarcinoma (2 papers, 2020 to 2022). A malignant tumor with glandular differentiation arising predominantly from Barrett mucosa in the lower third of the esophagus. "Moreover, miR-196a levels were conversely correlated with long-term survival esophageal adenocarcinoma and regulated the role of pro- and anti-apoptotic functions by targeting keratin 5, small prolinerich protein 2C, and S100 calcium-binding protein A9." (PMID 32903213, 2020).
food allergy (2 papers, 2022 to 2025). Gastrointestinal disturbances, skin eruptions, or shock due to allergic reactions to allergens in food. "In pediatric patients with AD, KRT5, KRT14, KRT16, FLG breakdown products, and AD clinical severity were predictive of concomitant food allergy." (PMID 40141720, 2025). "In addition, FLG breakdown products together with keratin 5 (KRT5), KRT14, KRT16 and AD clinical severity have been described as prognostic biomarkers for concomitant food allergy in children with AD." (PMID 36012878, 2022).
liver cancer (2 papers, 2017 to 2021). An epithelial or non-epithelial malignant neoplasm that arises from the liver. "We found that 6 mRNA expressions were significantly different (P<0.05), including GBP6 (guanylate binding protein), TMEM (transmembrane protein), CTCFL (liver cancer marker gene), KRT5 (keratin 5), LY6D (lymphocyte antigen) and TMEM179 (transmembrane protein)." (PMID 34714841, 2021).
liver disease (2 papers, 2020 to 2021). "We used our highest resolution keratin 1B structure as a template for homology-modeling the 1B heterotetramers of keratin 5/14 (associated with blistering skin disorders), keratin 8/18 (associated with liver disease), and keratin 74/28 (associated with hair disorder)." (PMID 32927888, 2020).
lymphoepithelial carcinoma (2 papers, 2012 to 2020). "Immunohistochemical staining revealed positive immunoreactivity for cytokeratin 5/6 and P63 in all the pulmonary lymphoepithelioma-like carcinoma tumors in the cohort." (PMID 31659278, 2020).
mesothelial tumor (2 papers, 2015 to 2016). "Thus, cytokeratin 5/6 and calretinin are useful to distinguish between mesothelial tumor and seminoma." (PMID 26106502, 2015).
nasal polyps (2 papers, 2020 to 2023). "KRT5 and KRT17 have been implicated in the regulation of cell proliferation and differentiation, and their upregulation may contribute to the abnormal growth of nasal polyps in ECRSwNP." (PMID 37867480, 2023). "The aim of this study was to investigate SM and accompanying levels of p63+Krt5+ (basal cell markers) cells in the nasal epithelium of patients with radiation-induced chronic rhinosinusitis (CRSr) and patients with chronic rhinosinusitis without nasal polyps (CRSsNP) compared to healthy controls." (PMID 32977822, 2020).
skin fragility (2 papers, 2021 to 2024). "KRT5 mutation altered the expression of DSG1, suggesting the regulatory role of this protein, thereby establishing that K5 contributes to the etiology of skin fragility directly or indirectly via DSG1." (PMID 34912369, 2021).
skin squamous cell carcinoma (2 papers, 2013 to 2022). A carcinoma arising from the squamous cells of the epidermis. "IKKα deletion mediated by keratin 5 (K5).Cre or K15.Cre in keratinocytes induces epidermal hyperplasia and spontaneous skin squamous cell carcinomas (SCCs) in Ikkα floxed mice." (PMID 24216703, 2013).
thymic carcinoma (2 papers, 2023). Thymic carcinoma (TC) is a type of thymic epithelial neoplasm characterized by a high malignant potential. "In an effort to understand why markers of tuft cells and ionocytes are preferentially expressed in thymic carcinomas, we investigated the distribution of the common squamous cell markers, KRT5 and TP63, in the adult thymus." (PMID 38201543, 2023).
viral pneumonia (2 papers, 2023 to 2024). Inflammation of the lung parenchyma that is caused by a viral infection. "Severe viral pneumonia can induce rapid expansion of KRT5+ basal-like cells in small airways and alveoli; this forms a scar-like structure that persists in the injured alveoli and impedes normal alveolar epithelium regeneration." (PMID 39352385, 2024). "Specifically, we found a central role for lung-resident CD8+ T cell-macrophage interactions in maintaining Krt8hi transitional and ectopic Krt5+ basal cell progenitors, thus impairing alveolar regeneration and driving fibrotic sequelae after acute viral pneumonia." (PMID 38077031, 2023).
acute lung injury (1 paper, 2023). A condition of lung damage that is characterized by bilateral pulmonary infiltrates (pulmonary edema) rich in neutrophils, and in the absence of clinical heart failure. "Krt5+SPC+ cells are a crucial subpopulation that promote the regeneration of functional alveolar epithelium by regeneration of AEC2s after acute lung injury." (PMID 37741976, 2023).
Hutchinson-Gilford progeria syndrome (1 paper, 2010). "The LMNA G608G transgenic mice targeted the expression of the Hutchinson-Gilford progeria syndrome (HGPS) mutation in keratin-5-expressing tissue led to a typical phenotype of HGPS." (PMID 21151901, 2010).
hypopharyngeal carcinoma (1 paper, 2025). Carcinoma, predominantly squamous cell, arising from the epithelial cells of the hypopharynx. "In hypopharyngeal carcinoma organoids, tumor basal cells were labeled with P63 (tumor protein 63) and KRT5 (keratin 5), and α-tubulin unspecifically labeled the entire structure, matching the phenotype of the primary hypopharyngeal carcinoma." (PMID 40001666, 2025).
Impaired glucose tolerance (1 paper, 2021). An abnormal resistance to glucose, i.e., a reduction in the ability to maintain glucose levels in the blood stream within normal limits following oral or intravenous administration of glucose. "AP mice that received Notch inhibitor showed that impaired glucose tolerance was reversed 7 and 15 days following AP, and increased numbers of newborn small islets due to increased differentiation of Krt5+ cells to beta cells to some extent." (PMID 34556631, 2021). "The Notch inhibitor application significantly increased the number of small islets and reversed the impaired glucose tolerance following AP in our murine model, which was to some extent attributed to the enhanced differentiation of Krt5+ cells toward beta cells." (PMID 34556631, 2021).
Insulin resistance (1 paper, 2019). Increased resistance towards insulin, that is, diminished effectiveness of insulin in reducing blood glucose levels. "Similarly, inhibition of insulin signaling decreased KRT5 and KRT10 protein levels, indicating that expression of these molecules is directly influenced by insulin resistance." (PMID 31581253, 2019).
intracranial meningioma (1 paper, 2014). A meningioma that arises within the cranial cavity. "Keratin 5/6 expression has not been previously studied in intracranial meningiomas." (PMID 24987706, 2014).
ischemic stroke (1 paper, 2026). A stroke disorder caused by obstruction of blood flow to the brain, due to thrombotic (local blood clot formation) or embolic (due to a blood clot or other material traveling from another site) event. "Interestingly, 203 upregulated and 212 downregulated genes, including Krt5, Krt14, Col17a1, and Pgam1‐ps1, were shared between EC‐specific KO and Vasculotide‐treated mice, indicating mutual pathways underlying the endothelial EphA4/Tie2 axis following ischemic stroke." (PMID 41164967, 2026). "Future studies may reveal whether modulating Krt5 in the meningeal environment could promote this avenue of collateral expansion following ischemic stroke." (PMID 41164967, 2026).
lung injury (1 paper, 2024). "After acute viral lung injury, loss of Sox2 enhances airway-to-alveolar epithelial fate transition and formation of Krt5+ dysplastic regeneration." (PMID 38182591, 2024).
lymphangioma (1 paper, 2019). A benign lesion composed of dilated lymphatic channels. "Studies have shown that MCPM biopsies are positive for a series of markers such as the proliferative protein Ki-67, cytokeratin 5/6, calretinin, BAP1, the transcription factor WT-1, and negative for endothelial markers (CD 31, CD 34, and factor VIII) whereas the opposite is true for lymphangioma." (PMID 31667333, 2019).
Lynch syndrome (1 paper, 2018). An autosomal dominant hereditary neoplastic syndrome characterized by the development of colorectal carcinoma and a high risk of developing endometrial carcinoma, gastric carcinoma, ovarian carcinoma, renal pelvis carcinoma, and small intestinal carcinoma. "Whole‐genome mRNA expression profiles of 41 tumors and immunohistochemical stainings against FGFR3, KRT5, CCNB1, RB1, and CDKN2A (p16) of 37 tumors from patients with Lynch syndrome were generated." (PMID 29791078, 2018).
malignant pleural mesothelioma (1 paper, 2009). A malignant neoplasm that arises from mesothelial cells in the pleura and shows a diffuse growth pattern. "In addition, it can also provide sufficient materials from forceps biopsy specimens to perform most histological tests including immunohistochemical staining of that for calretinin, WT1, cytokeratin 5/6, and D2-40 in a patient with malignant pleural mesothelioma." (PMID 19536345, 2009).
neuroendocrine carcinoma (1 paper, 2023). A malignant neuroendocrine neoplasm composed of cells containing secretory granules that stain positive for NSE and chromogranin. "Cytokeratin 5 and 6 (CK5 and CK6, respectively) are used to provide evidence of squamous lineage, indicating a diagnosis of SCC and ruling out poorly differentiated adenocarcinoma and well-differentiated neuroendocrine carcinoma." (PMID 36975459, 2023).
pancreatitis (1 paper, 2021). Inflammation of the pancreas. "The Krt5+ duct-like structures formed in pancreatitis might resemble acinar-to-ductal metaplasia (ADM), which contributes to the formation of premalignant lesions if persistent for a long time." (PMID 34556631, 2021).
penile tumors (1 paper, 2020). "The result showed robust injection-site-dependent orthotopic tumor formation and the orthotopic penile tumors remained salient SCC features such as keratin pearl and positivity for cytokeratin-5." (PMID 32358507, 2020).
Pruritus (1 paper, 2022). Pruritus is an itch or a sensation that makes a person want to scratch. "We identified several pruritus-associated genes increased by IDL, IDC and IDL + IDC (e.g., BRCA2, KRT5, TCF4), as well as several such genes decreased by IDL, IDC and/or IDL + IDC (e.g., IL2RG, TRPV3, TNFSF15, IL17RC)." (PMID 36430783, 2022).
retinoblastoma (1 paper, 2025). A malignant tumor that originates in the nuclear layer of the retina. "Among the most upregulated genes were KRT5, KRT19, LCN2, SLP1 and S100A9, while GNAT1, PDE6G, WIF1, FRZB, and RHO were among the top downregulated genes in retinoblastoma." (PMID 40395327, 2025).
salivary gland carcinoma (1 paper, 2017). A carcinoma that arises from the major or minor salivary glands. "Such a progenitor niche may be dysregulated in salivary gland carcinomas, as Krt5-positive populations are frequently amplified in these tumors." (PMID 28492365, 2017).
Sjogren syndrome (1 paper, 2017). An autoimmune disorder in which immune cells attack and destroy the glands that produce tears and saliva. "Similarly, Krt5-expressing cell populations have been observed to be expanded in Sjogren’s Syndrome epithelium." (PMID 28492365, 2017).
urethral carcinoma (1 paper, 2025). "The urethral carcinoma was positive for KRT5 and KRT7, consistent with urothelial origin." (PMID 39806204, 2025).
uterine diseases (1 paper, 2020). "Conditional loss of EZH2 in the uterus upregulated genes associated with uterine diseases, including keratin 5 (Krt5), keratin 15 (Krt15), the maternally-imprinted gene- H19, leucine-rich repeat-containing G-protein-coupled receptor 5 (Lgr5), and cell division cycle associated 5 (Cdca5)." (PMID 33732505, 2020).